EPHB4 (EPH receptor B4)
Diseases named in the same sentence as EPHB4 in open-access papers (continued):
Sharing a sentence is not in itself a finding about the gene and the disease.
ovarian tumor (3 papers, 2007 to 2022). "EPHB4 is a transmembrane receptor tyrosine kinase and recently reported as a novel ovarian tumor marker and a viable target for biological therapy." (PMID 22272227, 2012). "We confirmed EphB4 expression by Western blot in a select group of 10 ovarian tumour samples for which frozen tissues were available." (PMID 17353927, 2007). "We demonstrate a high level of expression of EphB4 in human ovarian tumours, which correlates with advanced stage and short survival." (PMID 17353927, 2007). "We then evaluated the role of EphB4 in ovarian tumour biology by achieving selective downregulation of EphB4 expression with specific siRNA and antisense ODNs." (PMID 17353927, 2007). "We also studied the biological significance of EphB4 expression in ovarian tumour cells lines in vitro and in vivo." (PMID 17353927, 2007). "All five malignant ovarian tumour cell lines tested expressed higher levels of EphB4 compared with the two benign cell lines." (PMID 17353927, 2007). "Ephrin-B3 has been described to correlate with EPHB4 expression in ovarian tumor specimens." (PMID 35328669, 2022). "EphB4 is thus a novel ovarian tumour marker and a viable target for biological therapy." (PMID 17353927, 2007). "Treatment of malignant, but not benign, ovarian tumour cell lines with progesterone, but not oestrogen, led to a 90% reduction in EphB4 levels that was associated with 50% reduction in cell survival." (PMID 17353927, 2007).
soft tissue sarcoma (3 papers, 2017 to 2022). A malignant neoplasm arising from muscle tissue, adipose tissue, blood vessels, fibrous tissue, or other supportive tissues excluding the bones. "From the point of view of tool model systems, when murine soft tissue sarcoma TMAs were assessed EphB4 and EphrinB2 expression was observed in 86% and 57% of seven eRMS cases tested." (PMID 28817624, 2017). "We have noticed that anti-EPHA2 and anti-EPHB4 as well as anti-ephrin-B1 therapeutic agents have been explored in bone and soft tissue sarcomas, albeit they could have also been tried in the clinical setting." (PMID 35563562, 2022). "A non-clinical study of EPHB4-CAR-T cell therapy targeting pediatric soft-tissue sarcoma is underway, and future clinical trials are proposed to be held in Japan." (PMID 33816783, 2021).
Stroke (3 papers, 2019 to 2025). Sudden impairment of blood flow to a part of the brain due to occlusion or rupture of an artery to the brain. "Moreover, ephrin-B2/EphB4 signaling has been shown to be involved in the restoration of the BBB and neurovascular repair mechanisms upon cerebral ischemia, underlining the importance of ephrin/Eph communication at the neurovascular interface for cellular responses to stroke." (PMID 30722785, 2019).
Telangiectasia (3 papers, 2024 to 2026). Telangiectasias refer to small dilated blood vessels located near the surface of the skin or mucous membranes, measuring between 0.5 and 1 millimeter in diameter. "On the other hand, pathogenic variants in EPHB4 explain the phenotype seen in CM-AVM2 syndrome, which is associated with various skin manifestations such as telangiectasias and angiospastic macules, epistaxis, and penetrance reported around 93%." (PMID 41063333, 2025). "A missense variant in EPHB4 was identified in a proband who met three Curaçao Criteria, and was described as having an ‘HHT-like’ vasculopathy due to profuse, non-HHT telangiectasia present on the lips since early childhood, now recognised as typical for EPHB4." (PMID 37586837, 2024).
bladder cancer (2 papers, 2014 to 2024). "Thus, EphB4 provides new mechanistic insights and novel diagnostic and therapeutic opportunities for bladder cancer." (PMID 25148033, 2014). "Expression of EphB4 in bladder cancer also provides the opportunity to monitor urine for EphB4-expressing cancer cells, a potential use as a tumor marker for diagnosis, prognosis and response." (PMID 25148033, 2014). "EphB4 expression is confirmed in bladder cancer cell lines including 5637 demonstrating strong EphB4 staining with little or no EphB2 protein expression by Western Blot and immunostaining." (PMID 25148033, 2014). "EphB4 knockdown in bladder cancer cell lines with specific siRNA lead to a dose dependent decrease in cell survival." (PMID 25148033, 2014). "We showed previously that EphB4 facilitates bladder cancer cell migration and invasion in vitro while EphB4 specific antisense oligodeoxynucleotides inhibited growth of bladder cancer xenografts in nude mice in vivo." (PMID 25148033, 2014). "Here, we studied the anti-tumor activity of sEphB4-HSA in bladder cancer xenograft models using the human bladder cancer cell line 5637 that has robust over-expression of EphB4." (PMID 25148033, 2014). "Furthermore we showed that EphB4 provided survival advantage to bladder cancer cells in vitro and in vivo." (PMID 25148033, 2014). "Previously, we showed that EphB4 was over-expressed in bladder cancer in a small number of cases." (PMID 25148033, 2014). "To elucidate the roles of EphB4 and EphB2 in TCC of the bladder, we examined the expression of EphB4 and EphB2 in normal and TCC surgical bladder specimens, and also in bladder cancer cell and immortalized normal urothelial cell lines." (PMID 25148033, 2014). "We have since developed a novel EphB4-EphrinB2 inhibitor sEphB4-HSA, which alone induces tumor regression in human bladder cancer xenograft." (PMID 25148033, 2014). "We found EphB4 is consistently over-expressed while EphB2 expression is predominantly absent in bladder cancer." (PMID 25148033, 2014).
Capillary malformation - arteriovenous malformation (2 papers, 2019 to 2022). "Mutations in the human EPHB4 gene are associated with various pathologies, such Capillary Malformation-Arteriovenous Malformation 2 and vein of Galen aneurysmal malformations, which are known to be associated with heart failure." (PMID 31782728, 2019).
carcinoma in situ (2 papers, 2014 to 2021). "We also observed trend towards higher EphB4 signal in tumors with accompanying carcinoma-in-situ." (PMID 25148033, 2014). "In addition, intensity of EphB4 staining in tumor specimens significantly correlated with higher tumor stage and trended to the presence of carcinoma in situ (CIS), a state of severe cellular dysplasia." (PMID 25148033, 2014). "Furthermore, EphB4 signal strength statistically correlated with higher tumor stage, and trended toward the presence of carcinoma in situ (CIS)." (PMID 25148033, 2014).
cardiac failure (2 papers, 2019 to 2022). "This supposed early expression of the EPHB4 variant was also correlated with a higher risk of high-flow cardiac failure." (PMID 35547535, 2022).
Cerebral arteriovenous malformation (2 papers, 2024 to 2025). "Despite these overlapping features, RASA1 mutations may still be more frequently associated with intracranial AVMs than EPHB4 mutations, although this remains statistically unproven." (PMID 41398316, 2025).
COVID-19 (2 papers, 2023 to 2024). A disease caused by infection with severe acute respiratory syndrome coronavirus 2. "EphB4, also associated with angiogenesis, was downregulated in our COVID-19 patients." (PMID 38760690, 2024).
dementia (2 papers, 2025). Loss of intellectual abilities interfering with an individual's social and occupational functions. "GALK1, EPHB4, and NOS3 showed significant region-dependent differential expression, with higher expression in the DLPFC of dementia cases and more pronounced regional differences compared to controls." (PMID 40799764, 2025). "Among the six PCTs with spatial transcriptomic data, pairwise Wilcoxon tests suggest elevated EPHB4 expression in endothelial cells from MCI and dementia cases with vascular pathology compared to cognitively normal controls." (PMID 40799764, 2025). "EPHB4 is disproportionately elevated in the DLPFC of AD cases and in the endothelial cells from the brain sections of individuals with MCI and dementia, highlighting additional key molecular markers orchestrating the shared mechanisms between vascular dysfunction and neurodegeneration." (PMID 40799764, 2025).
diabetes (2 papers, 2019 to 2021). "Further studies addressing the role and mechanisms by which the Ephrin-B2 receptor, EphB4, regulate pericytes/endothelial interaction in diabetes are needed to better understand diabetes-induced pathological cerebral neovascularization." (PMID 30620753, 2019).
endometriosis (2 papers, 2025). The growth of functional endometrial tissue in anatomic sites outside the uterine body. "The integration of MR and colozalization data allows us to conclude that EPHB4 is a Tier 1 gene, with the strongest evidence supporting its association with the pathogenesis of endometriosis." (PMID 40450304, 2025). "This is consistent with our research, which found that EPHB4 was strongly correlated with the risk of endometriosis using Mendelian randomization analysis." (PMID 40450304, 2025). "By integrating the results of SMR and colocalization analyses, we found that EPHB4 had a high level of correlation with the risk of developing endometriosis, while RSPO3 showed a moderate level of correlation." (PMID 40450304, 2025). "By integrating the results of SMR and colocalization analyses, we found that EPHB4 is strongly associated with the risk of endometriosis, with higher levels of EPHB4 correlating with an increased risk of the condition (PFDR < 0.05, PPH4 = 0.99)." (PMID 40450304, 2025). "The causal associations of PTGER4 and EPHB4 with endometriosis exhibited the highest robustness." (PMID 41353125, 2025). "Finally, we validated the EPHB4 mRNA expression level and protein abundance in peripheral blood from clinical samples, further confirming the association between EPHB4 and the pathogenesis of endometriosis." (PMID 40450304, 2025). "Taken together, these enrichment analyses collectively depict a clear picture: EPHB4, acting as a key membrane receptor, regulates downstream cell migration and angiogenesis processes by activating the ephrin signaling pathway, thereby playing a “risk” role in the pathogenesis of endometriosis." (PMID 41353125, 2025). "The results showed that the relative protein expression level of EPHB4 in plasma was significantly higher in the endometriosis group compared to the control group (P < 0.05)." (PMID 40450304, 2025). "The protein expression level of EPHB4 in plasma from 12 patients with endometriosis and 12 controls was assessed using ELISA." (PMID 40450304, 2025). "Taken together, the causal associations of EPHB4 and PTGER4 with endometriosis received the most robust support." (PMID 41353125, 2025). "ELISA and RT-qPCR analyses showed that the EPHB4 protein abundance in plasma and mRNA expression levels in PBMCs were significantly higher in the endometriosis group compared to the control group (P-value < 0.05)." (PMID 40450304, 2025). "RT-qPCR analysis showed that the relative mRNA expression level of EPHB4 in PBMCs was significantly higher in the endometriosis group compared to the control group (P < 0.05)." (PMID 40450304, 2025). "Validation using clinical samples further confirmed that EPHB4 mRNA expression in PBMCs and protein abundance in plasma were significantly elevated in patients with endometriosis compared to controls." (PMID 40450304, 2025). "The results showed that both the mRNA expression levels of EPHB4 in PBMCs and the protein abundance of EPHB4 in plasma were significantly elevated in patients with endometriosis compared to the control group." (PMID 40450304, 2025). "Lastly, while potential drugs for treating endometriosis, such as EPHB4 inhibitors, were discussed, experimental validation in endometriosis models has not been conducted." (PMID 40450304, 2025). "After colocalization analysis, we identified that EPHB4 is considered to support high-level evidence of colocalization with endometriosis (PPH4 = 0.993), while RSPO3 is considered to support moderate-level evidence of colocalization with endometriosis (PPH4 = 0.783)." (PMID 40450304, 2025). "We found that the druggable genes EPHB4, CD109, SAA1, SAA2, FSHB, and SEZ6L2 may be associated with the pathogenesis of endometriosis and are potential therapeutic targets for drug treatment." (PMID 40450304, 2025).
endometriosis (continued). "This study indicates that the druggable genes EPHB4, CD109, SAA1, SAA2, FSHB, and SEZ6L2 may be associated with the pathogenesis of endometriosis and are potential therapeutic targets for drug treatment." (PMID 40450304, 2025). "Meanwhile, our study suggested that higher levels of EPHB4, RSPO3, FSHB, and SEZ6L2 were associated with an increased risk of endometriosis, while lower levels of CD109, SAA1, and SAA2 were also associated with an increased risk of endometriosis." (PMID 40450304, 2025). "Therefore, EPHB4 represents a promising therapeutic target for the treatment of endometriosis." (PMID 40450304, 2025). "To further investigate the potential pathogenic mechanisms of PTGER4 and EPHB4 in endometriosis and to elucidate the targets of relevant non-steroidal anti-inflammatory drugs (NSAIDs), we performed a functional enrichment analysis on these core genes based on drug-target interactions." (PMID 41353125, 2025). "Thus, EPHB4 may mediate the pathogenesis of endometriosis through SDF-1/CXCR4-driven angiogenesis." (PMID 40450304, 2025).
epistaxis (2 papers, 2025). Bleeding from the nose. "Indeed, epistaxis and mucocutaneous telangiectasia, hallmark features of HHT, have also been reported in a subset of CM-AVM patients, especially those with EPHB4 mutations." (PMID 41398316, 2025).
hemorrhage (2 papers, 2022 to 2023). Loss of blood from the vascular compartment to the exterior or into nonvascular body space as a result of rupture or severance of the blood vessels. "Twelve single nucleotide polymorphisms (SNPs), including IL6 rs1800795, IL17A rs2275913, MMP9 rs9509, VEGFA rs1547651, and EPHB4 rs314353, rs314308, and rs314313, were associated with bAVM-related hemorrhage." (PMID 37065486, 2023). "This led to the identification of statistically significant association between bAVM-related hemorrhage and twelve heritable variants of seven genes (IL6, APOE, IL1B, IL17A, MMP9, EPHB4, and VEGFA) involved in the inflammatory and angiogenic signaling pathways." (PMID 37065486, 2023). "Interestingly, two proteins (uPA and PRTN3) in the CB group and three proteins (vWF, uPA, and EPHB4) in the RB group were also the significant proteins selected by LASSO logistic regression and random forest, among which only PRTN3 was related to hemorrhage and coagulation in the RF group." (PMID 36704472, 2022).
myeloma (2 papers, 2011 to 2014). "In line with this, interference with the ephrinB2/EphB4 axis by myeloma cells represses bone formation." (PMID 25485970, 2014).
non-small cell lung carcinoma (2 papers, 2021 to 2025). A group of at least three distinct histological types of lung cancer, including non-small cell squamous cell carcinoma, adenocarcinoma, and large cell carcinoma. "Further research results indicate that EPHB4 is currently undergoing clinical trials in solid tumors and non-small cell lung cancer." (PMID 41261599, 2025). "In addition, the IL6ST targeted drug siltuximab is undergoing I/II trials for solid tumors, while the EPHB4-targeted drug tesevatinib is undergoing I/II trials for solid tumors and non small cell lung cancer." (PMID 41261599, 2025).
papillary carcinoma (2 papers, 2020 to 2021). A malignant epithelial neoplasm characterized by a papillary growth pattern. "It has been reported that high EphB4 expression enhanced the growth and migration of pancreatic, colorectal and papillary thyroid carcinoma, and such effect could be reversed by EphB4 knockdown, making EphB4 a promising target for cancer treatment." (PMID 32801343, 2020).
prostate tumor (2 papers, 2005 to 2019). "The EPHB4 receptor is implicated in the development of several epithelial tumors and is a promising therapeutic target, including in prostate tumors in which EPHB4 is overexpressed and promotes tumorigenicity." (PMID 31641103, 2019). "Our results indicate that EPHB4 inhibition decreases prostate tumor cell proliferation and increases cell death in vitro." (PMID 31641103, 2019). "To localize the expression of EphB4 in normal prostate and tumour tissue, we performed immunohistochemistry using an EphB4-specific antibody on 15 prostate tumour samples collected by transurethral resection." (PMID 16171530, 2005).
squamous cell carcinoma (2 papers, 2013 to 2021). A carcinoma arising from squamous epithelial cells. "Six, nine, and 23 percent of adenocarcinoma, small cell carcinoma, and squamous cell carcinoma tissues, respectively, were found to contain more than three EPHB4 gene copies, with 14% of squamous cell carcinoma tissues having more than 10 copies." (PMID 23844053, 2013). "For example, a phase I dose-escalation study of sEphB4-HAS, a soluble fusion protein that binds and sequesters the ligand for EphB4, in combination with chemotherapy, cetuximab and radiotherapy is ongoing in squamous cell carcinoma of head and neck patients (NCT04091867)." (PMID 34440844, 2021).
vein of Galen aneurysmal malformation (2 papers, 2019 to 2021). "Heterozygous mutations in EPHB4 are reported to cause CM-AVM2, vein of Galen aneurysmal malformation, LRFH, and central conducting lymphatic anomaly (CCLA), but the mechanisms underlying these different presentations remain unclear." (PMID 34403370, 2021).
anterior uveitis (1 paper, 2026). Inflammation of the iris and anterior chamber of the eye. "Between the patients with panuveitis and patients with only posterior or anterior uveitis, serum Ang-1 (P < .001), Tie-2 (P < .001), EphrinB2 (P < .001), EphB4 (P = .001), and endocan (P = .002) levels had statistically significant differences." (PMID 42071810, 2026).
Arthritis (1 paper, 2022). Inflammation of a joint. "In this model of postmenopausal arthritis, YSJB administration improved arthritis progression and prevented bone destruction by reducing osteoclastogenesis and regulating the expression of ephrinB2, ephB4, and NFATc1 in the BM." (PMID 36249763, 2022).
Ascites (1 paper, 2007). Accumulation of fluid in the peritoneal cavity (between the layers of the peritoneum that lines the abdomen). "Ninety per cent of patients with EphB4 overexpression had ascites compared with 49% of patients without EphB4 overexpression (P<0.001)." (PMID 17353927, 2007).
bladder tumor (1 paper, 2014). "Treatment of bladder tumor xenograft with an EphB4 inhibitor sEphB4-HSA leads to 62% tumor regression and complete remission when combined with Bevacizumab." (PMID 25148033, 2014). "An inhibitor of EphB4 in a bladder tumor xenograft model significantly inhibited tumor cell proliferation and angiogenesis, and also induced apoptosis and overall tumor regression." (PMID 25148033, 2014).
brain cancer (1 paper, 2014). A primary or metastatic malignant neoplasm affecting the brain. "The kinase CSNK1E had been previously associated only with non-brain cancers, while HIPK2, LYN, and EPHB4 have been suggested as targets for anti-tumor therapies." (PMID 25236784, 2014).
brain infarction (1 paper, 2022). Tissue necrosis in any area of the brain, including the cerebral hemispheres, the cerebellum, and the brain stem. "EA could accelerate capillary formation in the brain infarction area of MCAO rats through up-regulating EphB4 and EphrinB2 mRNA and increasing the level of Src and PI3K, manifesting that the formation of new vessels after EA was partly to regulated by EphB4/EphrinB2 mediated Src/PI3K signal pathway." (PMID 36388196, 2022).
breast tumours (1 paper, 2009). "EPHB4 has not been used as a marker of disseminated breast tumour cells prior to this study." (PMID 19500345, 2009).